ENSG00000280371 ( gene)
Diseases named in the same sentence as ENSG00000280371 in open-access papers (continued):
Sharing a sentence is not in itself a finding about the gene and the disease.
tumor (continued). "MALAT1 is highly expressed in PTC, as an oncogene to promote tumor EMT, and as a tumor suppressor gene to inhibit tumorigenesis in poorly differentiated and anaplastic thyroid carcinoma." (PMID 34930256, 2021). "In conclusion, our study suggested that miR-513b-5p inhibited the expression of TRIB1 and exerted a tumor suppressor gene in Weri-RB1 cells." (PMID 34589612, 2021). "PRICKLE1 has been reported to be a negative regulator of the Wnt/beta-catenin signaling pathway and is a putative tumor suppressor gene in HCC." (PMID 34660596, 2021). "We found that PJVK was downregulated in tumour tissues, and its low expression predicted poor survival rates, indicating that it functioned as a tumour suppressor gene in this study." (PMID 33828074, 2021). "Altogether, these studies suggested that LINC01296 can present different expression levels in different tumor types, both as an oncogene or a tumor suppressor gene." (PMID 34515611, 2021). "Another valuable finding from our studies was that estrogen also upregulated a tumor-suppressor gene, IL-24, only in GS3." (PMID 34944995, 2021). "Since MLL3 acts as a tumor-suppressive gene in multiple cancer types, we examined its function on TNS3 in several cancer cell lines, including U2OS, HeLa, 769-P, and MDA-MB-231." (PMID 33824309, 2021). "The suppressor of cytokine signaling 1 (SOCS1) is a tumor-suppressor gene and suppresses cytokine signaling and destroys the HPV E7 protein." (PMID 35096000, 2021). "It acts as an oncogene in some tumors to mediate the tumor process, while in others it plays a role as a tumor suppressor gene." (PMID 34356052, 2021). "Collectively, these findings are consistent with the notion that KrasWT acts as a relative tumor-suppressor gene in the presence of oncogenic Kras and that its deletion leads to the hyperactivation of the Kras pathway." (PMID 34172714, 2021). "Programmed cell death 4 (PDCD4) is a proinflammatory tumor-suppressor gene which helps to prevent the transition from chronic inflammation to cancer." (PMID 33288677, 2021). "Somatic copy-number alterations (SCNAs) affect a larger fraction of the genome, which can potentially activate an oncogene or inactivate a tumor suppressor gene." (PMID 34945000, 2021). "miR-149 is abnormally expressed in several malignant tumors and can be used as an oncogene or tumor suppressor gene to regulate the biological behavior of tumor cells." (PMID 34957298, 2021). "In lymphoid tissues far away from tumor cell areas expression of the immune-related gene CD74 was observed while in tissues in close proximity to tumor cell areas, expression of the immune-related gene IGLL5 was seen." (PMID 35008286, 2021). "A discrepancy of the result is that FBXW7 is a cancer suppressor gene and there are proofs that mutation of FBXW7 can increase the degree of malignancy of tumor cells." (PMID 35712679, 2021). "Meanwhile, miR-98-5p has been reported as a tumor suppressor gene to inhibit tumor growth and metastasis in a variety of cancers, and associated with resistance to anti-tumor drug therapy." (PMID 34837929, 2021). "FOXJ1 is hypermethylated in BRCA cell lines and clinical tissue samples, revealing its role as a putative tumor suppressor gene." (PMID 33688372, 2021). "CA9, a well-known hypoxia-induced gene, plays critical roles in promoting tumor progression and hypoxia adaptation." (PMID 34493285, 2021). "BLM helicase has been implicated in various DNA transactions where it acts as a bonafide tumor suppressor gene." (PMID 33777104, 2021). "For instance, H19 can exhibit proto‐oncogene activities that promote tumour development and growth, but can act as a tumour suppressor gene in other tumours by inhibiting tumour proliferation, metastasis and invasion." (PMID 33236528, 2021). "A previous study indicated that miR-137 plays a role as a tumour suppressor gene in multiple tumours." (PMID 33413360, 2021).
tumor (continued). "As one of the least studied sirtuin family members, the mitochondrial sirtuin SIRT4 is a tumor suppressor gene in various cancers." (PMID 32863939, 2020). "Lumican has two opposite effects on the occurrence and the development of tumors as it can act as an oncogene or a tumor suppressor gene." (PMID 32500021, 2020). "Several studies have suggested that SEPT9 acts a tumor suppressor gene and plays an important role in the regulation of cell division during its hypermethylation in liver carcinogenesis." (PMID 33178361, 2020). "Recent studies also revealed that TIPE1 probably serves as a tumor suppressor gene in several tumor types." (PMID 33520705, 2020). "It has been reported that the CTCC-binding protein (CTCF) acts as a tumor suppressor gene by regulating the expression of tumor-related genes." (PMID 33256112, 2020). "Recently, the anti-tumor effect of LHPP has been further demonstrated: LHPP is considered as a tumor suppressor gene of hepatocellular carcinoma by the PI3K/AKT signaling pathway, and its low expression leads to a decrease in patient survival rate." (PMID 32186702, 2020). "Our previous studies showed that promoter methylation caused Upf1 downregulation in HCC and that Upf1 regulated hepatocarcinogenesis and acted as a tumor suppressor gene in HCC." (PMID 32802196, 2020). "Several studies have reported that miRNA-204 expression is downregulated in tumor tissues than in normal tissues, and it is thus generally regarded to be a tumor suppressor gene." (PMID 32158466, 2020). "On the other hand, miR-552 targets PTEN, a key tumor suppressive gene, and thus promotes OC growth and metastasis." (PMID 32984052, 2020). "PDCD4, one of the targets of miR-21, was demonstrated to be a tumor-suppressor gene and the target of procancer miRNAs (Lankat-Buttgereit and Göke, 2009)." (PMID 33329700, 2020). "In some studies, low expression of lncRNA in cancer tissues has been found to act as a tumor suppressor gene and inhibit tumor progression." (PMID 33174687, 2020). "CpG island methylator phenotype (CIMP) can result in the silencing of key genes important for tumor progression, including the tumor‐suppressor gene, CDKN2A, and the DNA mismatch repair gene, MLH1." (PMID 33005848, 2020). "Our results showed that miRNA‐96‐5p is an miRNA that functions as an oncogene, and FOXO3 is a tumor suppressor gene." (PMID 32100957, 2020). "Ras association domain family 1A (RASSF1A), a well-recognized tumor suppressive gene in various types of tumors, is a putative tumor suppressor gene located on the 3p21.3 locus 38-40." (PMID 33193895, 2020). "In the present study, miR-192 was demonstrated to show low expression in OSA tissues and cells, supporting that miR-192 served as a tumor suppressor gene in OSA, which is consistent with the previous study." (PMID 33097010, 2020). "In this study, we found that miR-330-5p was downregulated in BC and functioned as a tumor-suppressor gene in BC." (PMID 33176280, 2020). "Several investigations demonstrated that lncRNA GAS5 can act as a tumor suppressor gene by different actions." (PMID 32727450, 2020). "A previous study reported that methylation of CCNA1, a tumor suppressor gene, can differentiate between low and high grade lesions." (PMID 32102526, 2020). "SLC4A4 mRNA expression depends exclusively on hypoxia inducible factor 1 subunit alpha, a tumor suppressor gene in ccRCC." (PMID 30668544, 2019). "Tet methylcytosine dioxygenase 2 (TET2) is a tumor suppressor gene that is inactivated in a wide range of hematological cancers." (PMID 31231651, 2019). "In contrast several lines of evidence provide insights into potential mechanism by which cdk10 act like a putative new tumor suppressor gene in multiple types of human cancers." (PMID 31413335, 2019).
tumor (continued). "Earlier studies also prove SNHG20 as tumor-suppressive gene in other tumors consistent with our findings." (PMID 30744670, 2019). "Particularly, TSLC1 (CADM1; cell adhesion molecule 1) located in 11q23.3 has an important role as tumor suppressor gene in NB and has also been related in oncogenesis." (PMID 31551474, 2019). "TCF12, which is known to be involved in the regulation of cell growth and differentiation, has been reported to function as an oncogene or a tumor suppressor gene in the progression of various malignant tumors." (PMID 31534521, 2019). "PTEN acts as a tumor suppressor gene through inhibition of the PI3K/AKT signaling pathway, which participates in the regulation of various biological functions, including cellular growth, metabolism and survival." (PMID 31469661, 2019). "To conclude, we show that PDCD4, a tumor suppressor gene suppressed in many cancers, is regulated through a relationship between miR-21 and miR-499." (PMID 31235478, 2019). "Adenine-thymine (AT)–rich interactive domain-containing protein 1a (ARID1a) is a tumor suppressor gene." (PMID 30811493, 2019). "Based on above results, we considered that the NLRP3 was tumor suppressor gene in ccRCC and the NLRP3 inflammasome is an important functional effector of LXRα in ccRCC cells for the first time." (PMID 30770793, 2019). "Chmp1A and CADM2, belonging to cell adhesion molecules family, had been found to be a tumor suppressor gene in RCC." (PMID 32038722, 2019). "All the data indicated that LINC00982 acts as a tumor suppressor gene, and revealed LINC00982-PI3K/AKT signaling pathway regulatory network contributes to PTC." (PMID 31262968, 2019). "In summary, this study reports that miR-29c was frequently downregulated in NSCLC and acts as a tumor suppressor gene in NSCLC cells by negatively regulating AKT2." (PMID 29789623, 2018). "The Bax gene is a tumor suppressor gene, and Bcl-2 is an antiapoptotic gene that antagonizes the function of Bax." (PMID 29636773, 2018). "S100A2 has been identified as a markedly downregulated gene in tumor-derived mammary epithelial cell lines and was assumed as a tumor suppressor gene." (PMID 30558666, 2018). "Although GLS2 has been suggested to act as a tumor suppressor gene, nothing is known about its role in S. aureus infection." (PMID 30289878, 2018). "Several studies have suggested possible roles of GSK-3β as a tumor suppressor gene in HCC, whereas, other studies have indicated that GSK-3β is a potential therapeutic target for this cancer." (PMID 29445085, 2018). "In past decades, studies revealed that PARK2 was a vital tumor suppressor gene in many malignant solid tumors." (PMID 29515107, 2018). "Based on these reports, it seems that miR-511 displays contrasting roles in different tumor types, implying that the cancer type determines the role of miR-511 as an oncogene or tumor suppressor gene." (PMID 28114950, 2017). "CDH5 is a non-histone chromosomal protein belonging to the SWI2/SNF2-related superfamily of ATPases and a potent tumour suppressor gene." (PMID 28144288, 2017). "PR domain zinc finger protein 5 (PRDM5), a member of the Kruppel-like zinc finger family is an important tumour suppressor gene and has been found to be methylated in gastric human carcinomas like." (PMID 28144288, 2017). "Checkpoint with Forkhead-associated and Ring finger domains (CHFR) is a G2/M checkpoint and tumor-suppressor gene." (PMID 29312643, 2017). "It has been reported that miR-195-5p is a tumor-suppressor gene that mainly suppresses cell proliferation and invasion and is down regulated in cancer patients." (PMID 28498798, 2017). "CTCF is a haploinsufficient tumour suppressor gene with diverse normal functions in genome structure and gene regulation." (PMID 28319062, 2017).
tumor (continued). "miR-184 in human cancer appears to be context-dependent with roles as an oncogene and a tumour suppressor gene." (PMID 28736583, 2017). "Altogether, these results demonstrate a role for SLC7A11-AS1 in cell proliferation and cell cycle progression and as a tumor suppressor gene." (PMID 29348845, 2017). "This expression pattern of these two IQGAP isoforms across different cancer types supports the notion that IQGAP2 possibly plays the role of a tumor suppressor gene whereas IQGAP3 is more likely to be an oncogene." (PMID 29073199, 2017). "PSP94 is a suppressor of tumor growth and metastasis; SLIT2 inhibits prostate cancer cell proliferation and invasion; and CDKN2A is a critical tumor suppressor gene." (PMID 28410242, 2017). "Depending on tumor type and disease stage, as well as therapy, BCL2 seems to be able to act as both an oncogene and a tumor suppressor gene." (PMID 28396899, 2017). "It has been shown that POU2F1 acts not only as an oncogene but also as a tumor suppressor gene in different cancers." (PMID 28489585, 2017). "The lncRNA growth arrest special 5 (GAS5), was previously identified to be down-regulated and functions as a tumor suppressor gene in many kinds of cancers." (PMID 27863421, 2016). "We observed a distinct increase of SLC6A3 mRNA (>200-fold) in ccRCC tissue compared to the normal parenchyma indicating a role as tumor suppressor gene." (PMID 26831905, 2016). "In conclusion, our study indicates that miR-381 functions as an oncogene, and LRRC4 serves as a tumour suppressor gene in OS." (PMID 27612424, 2016). "BECN1, an autophagy initiation gene also involved in ploidy homeostasis, increases tumor formation when monoallelically deleted." (PMID 27391266, 2016). "Among the top 15 predicted targets (ordered by increasing mirSVR score), VSNL1 is a known tumor-suppressor gene regulating cell migration in several cancer types." (PMID 26683098, 2016). "This gene has been extensively studied in the past decade and has been characterized as an apoptosis-inducer and tumor-suppressor gene." (PMID 27124579, 2016). "The findings presented here reinforce the role of TAp73 as tumor suppressor gene and indicate that the regulation of cellular metabolism by TAp73 contributes to its tumor suppressor function." (PMID 27119504, 2016). "MiR-342 has also been shown to act as a tumor suppressor gene in CRC development by regulating aberrant DNA hypermethylation." (PMID 26569605, 2015). "Epigenetic inactivation of GATA4 by promoter hypermethylation was observed in both AML cell lines and pediatric AML samples; our study implicates GATA4 as a putative tumor suppressor gene in pediatric AML." (PMID 26490736, 2015). "This gene regulates neuronal and muscle differentiation and is a tumor suppressor gene in several types of cancer." (PMID 26112950, 2015). "The present study demonstrate that up-regulator of cell proliferation (URGCP), a recently identified tumor-promoting gene found in several tumor types, is markedly overexpressed in human NSCLC cell lines and clinical NSCLC samples." (PMID 26429875, 2015). "Our data shows that miR-216b, acting as a tumor suppressor gene, inhibits cell proliferation, colony formation and induces G0/G1 cell cycle arrest, whereas, UCA1 can overturn these inhibitory effects of miR-216b on HCC cells." (PMID 25760077, 2015). "In fact, the identifying Beclin-1 as a tumor suppressor gene in human cancer provided early evidence for the tumor suppressive role of autophagy." (PMID 26561802, 2015). "We found that another solute carrier gene, SLC17A7, is also a candidate bivalent tumor suppressor gene." (PMID 25749033, 2015).
tumor (continued). "The role of miR-100 in cancer is quite contradictory, since it can behave either as an oncogene or as a tumor suppressor gene, depending on the tumor type." (PMID 25537513, 2015). "In contrast, mammary gland tumorigenesis was enhanced in Apc1638NCtnnb1+/- mice, perhaps because Ctnnb1 functions as a tumor suppressor gene in the mammary gland tumors via β-catenin’s role in E-cadherin-dependent tumor suppression." (PMID 26528816, 2015). "An increasing body of evidence shows that PTEN functions as a tumour suppressor gene in some tissues, and its tumour suppressor activity is dependent on its lipid phosphatase activity, which negatively regulates the PI3K-AKT-mTOR pathway." (PMID 26511107, 2015). "RECK is thought to be a tumor invasion and metastasis suppressor gene, and was also found to inhibit tumor cell growth and motility in both lung and bladder cancer." (PMID 25084400, 2014). "N-myc downstream-regulated gene 2 (NDRG2), a novel tumour suppressor and cell stress-related gene, is involved in many cell metabolic processes, such as hormone, ion and fluid metabolism." (PMID 24636131, 2014). "On the other side, miR-17-92 cluster also can negatively regulate the oncogene E2F1 or MYC to inhibit cell cycle progression as the tumor suppressor gene." (PMID 24722426, 2014). "Recently, SMG1 was suggested as a novel potential tumor suppressor gene, particularly in hypoxic tumors." (PMID 25257528, 2014). "BRG1 gene is frequently deleted or mutated in a variety of tumor cell lines, implicating BRG1 as a potential tumor suppressor gene, and mouse models have confirmed the tumor suppressor activities of BRG1." (PMID 25157878, 2014). "HES1 has been suggested to have both oncogenic and tumor suppressive functions, whereas KLF10 has been suggested to be a tumor suppressor gene." (PMID 24885297, 2014). "The CIS RPS6KA5 was deleted in approximately 25% of GBMs and was also found in the top 7% of genes down-regulated at the mRNA level in the microarray dataset, implicating it as a candidate tumor suppressor gene." (PMID 25423036, 2014). "The results suggested that miR-302b acted as a tumor suppressor gene in ESCC by inhibiting proliferation, inducing apoptosis, and repressing invasion." (PMID 24438167, 2014). "These two previous instances, and the computational and experimental effort detailed here, establish AGTR1 as a potential tumor suppressor gene in HNSCC." (PMID 25186767, 2014). "The tumor suppressor gene and epithelial cell marker E-cadherin (Cdh1) was markedly up-regulated and the oncogenic transcription factor Myc was down-regulated by Tcf7l2 silencing." (PMID 25414334, 2014). "The expression of OGN was absent in several cancer cell lines, implicating its potential role as a tumor suppressor gene in cancer biology, although its physiological function has not been fully elucidated." (PMID 24587265, 2014). "Our study indicates for the first time that, in addition to its role in brain development, MCPH1 also functions as a tumor suppressor gene and is regulated by miR-27a." (PMID 23472065, 2013). "A loss of function of DLEC1 was previously related with several cancers, suggesting that DLEC1 acts as a tumor suppressor gene." (PMID 24222856, 2013). "In the past research, NDRG2 was shown as a tumor suppressor gene in many kinds of tumors, which promoted differentiation and apoptosis and inhibited proliferation in a variety of tumors." (PMID 23307246, 2013). "The mechanism of the Notch receptor function as an oncogene or tumor suppressor gene remains to be elucidated." (PMID 23599800, 2013). "This protein seems to have dual functions in tumorigenesis, where it can act either as a tumor promoting gene or as a tumor suppressor gene." (PMID 24302991, 2013).